CTSZ (cathepsin Z)
Diseases named in the same sentence as CTSZ in open-access papers (continued):
Sharing a sentence is not in itself a finding about the gene and the disease.
prostatic intraepithelial neoplasia (1 paper, 2023). "The high expression level of CTSZ, found in prostatic intraepithelial neoplasia and PCa, may contribute a significant role in the early tumorigenesis of PCa, which is further clarified by RT-qPCR." (PMID 37122696, 2023).
synovitis (1 paper, 2021). Inflammation of a synovial membrane. "Except for LCP1, CTSZ and PTPRC, all proteins have never been described in human synovitis." (PMID 35008858, 2021).
systemic sclerosis (1 paper, 2022). A chronic disorder, possibly autoimmune, marked by excessive production of collagen which results in hardening and thickening of body tissues. "One of these gene regions, CTSZ, was previously reported to be hypomethylated in MS in post-mortem brain tissue and to also be associated with risk of systemic sclerosis." (PMID 36685876, 2022).
thyroid (1 paper, 2025). "The standout finding of cathepsin Z in our results, showing a significant correlation with PTC risk, pivots our discussion to its potential unique role in thyroid carcinogenesis." (PMID 39791166, 2025).
type 1 diabetes (1 paper, 2025). "Notably, overexpression of CTSH and CTSZ have been identified as risk factors for type 1 diabetes, a disease that involves autoreactive T cells targeting pancreatic beta cells." (PMID 41283441, 2025).
tumor (46 papers, 2008 to 2025). "Some studies present TAM secreting factors associated with tumor progression, including cathepsin Z (CtsZ), a protease which promotes tumor proliferation and invasion." (PMID 40565098, 2025). "CTSZ is a lysosomal cysteine protease that has been implicated in tumor progression across various malignancies." (PMID 40568593, 2025). "Altogether, these results show that the Macro_APOE/CTSZ abundance associates with high‐grade tumor in patients with CRC by contributing to immunosuppressive TME." (PMID 36587392, 2023). "In order to figure out the underlying causes that Macro_APOE/CTSZ specifically upregulated glutamate transport and glutamate‐to‐glutamine metabolic pathway, we analyzed the glutamate‐related metabolic genes in tumor cells." (PMID 36587392, 2023). "In some of these studies, CTSZ was found in tumor-associated macrophages, indicating that this protease plays a role in the antitumor immune response." (PMID 34378678, 2021). "Histological studies confirmed that the lesions were caused by the extravasation, and the subsequent tumor growth of CTSZ-transfected HCC cells into the livers." (PMID 21966391, 2011). "Collectivaly, higher CTSZ implicated a poor clinical outcomes in the context of tumor." (PMID 40568593, 2025). "In some of these studies, CTSZ was found in tumor-associated macrophages." (PMID 37274256, 2023). "To assess whether Macro_APOE/CTSZ was associated with histologic grade of the tumor, we found these immunosuppressive markers were significantly upregulated in high‐grade tumors compared with low‐grade in CRC‐MMRp and CRC‐MMRp." (PMID 36587392, 2023). "Notably, within the small set of genes associated with tumor-enriched bacterial signatures, we observed cathepsin Z, a tumor associated protease, and interleukin-8, an inflammatory cytokine and mediator of innate immunity secreted by activated macrophages." (PMID 24450771, 2013). "Therefore, another mechanism of CTSZ in tumor metastasis is associated with its role in reducing cell-cell adhesion by digesting the extracellular matrix ingredients, thus makes it easier for tumor cells to migrate to the adjacent tissues." (PMID 21966391, 2011). "Our study highlights CTSZ as a potential prognostic and therapeutic biomarker in PCa, demonstrating that its overexpression is associated with immune cell infiltration, immune checkpoint molecule expression (such as PD-1 and PD-L1), tumor mutation burden, and key oncogenic pathways." (PMID 40568593, 2025). "Notably, CTSZ overexpression is linked to an immune-enriched yet immunosuppressive tumor microenvironment, characterized by increased infiltration of regulatory T cells and M2 macrophages, as well as upregulation of immune checkpoint molecules such as PD-1 and PD-L1." (PMID 40568593, 2025). "Pan-cancer analysis revealed significantly elevated CTSZ expression in 26 tumor types (all P < 0.05), with particularly high levels in PCa." (PMID 40568593, 2025). "Recent studies have underscored the potential involvement of cathepsin Z (CTSZ) in modulating the progression of diverse tumor types." (PMID 40568593, 2025). "We also found that CTSZ expression was strongly correlated with ImmuneScore (P < 0.001) and StromalScore (P < 0.001), indicating a more abundant immune presence within the tumor microenvironment of PCa with high CTSZ expression." (PMID 40568593, 2025). "GSEA identified CAM, VEGF, and STAT signaling pathways as potential mechanisms through which CTSZ promotes tumor progression, highlighting its potential as both a prognostic biomarker and therapeutic target in PCa." (PMID 40568593, 2025). "CTSZ expression showed a significant positive correlation with the infiltration of diverse immune cells, suggesting an overall immune-enriched tumor microenvironment." (PMID 40568593, 2025).
tumor (continued). "The tumor-promoting function of CtsZ is mediated by the Arg-Gly-Asp (RGD) motif in its proenzyme domain, which regulates interactions with integrins and the extracellular matrix." (PMID 40129966, 2025). "CTSZ is expressed in several primary tumor types, such as PCa (prostate cancer), colorectal, gastric, liver, melanoma, and pancreatic neuroendocrine tumors." (PMID 37274256, 2023). "Glutaminase (GLS), converting glutamine to glutamate, was downregulated in tumor cells compared with Macro_APOE/CTSZ, in CRC samples." (PMID 36587392, 2023). "We found that the proportion of Macro_APOE/CTSZ was significantly higher in tumor than normal tissues and accounted for more than 20% of macrophages in most CRC patients." (PMID 36587392, 2023). "In particular, we uncovered a tumor‐associated macrophage (TAM) subpopulation, APOE+CTSZ+TAM, that was present in high proportions in tumor samples and exhibited immunosuppressive characteristics through upregulating the expression of anti‐inflammatory genes." (PMID 36587392, 2023). "We also identified a correlation between CTSZ methylation level in BC and tumor stage, ER status and HER2 status." (PMID 37274256, 2023). "Glutamate‐to‐glutamine metabolic pathway and GLUL expression, specifically activated and overexpressed in Macro_APOE/CTSZ, were higher in high‐grade compared with low‐grade tumor samples." (PMID 36587392, 2023). "We demonstrated that p54nrb dependent regulation of cathepsin-Z and gelsolin was universal across all the three tumor cell lines investigated." (PMID 35444189, 2022). "Cathepsin-Z promotes tumor cell proliferation via integrins, which aligns well with the decreased tumor cell viability observed in p54nrb depleted cells." (PMID 35444189, 2022). "We first provided a comparative overview of the CTSZ mRNA expression in different tumor and non-tumor sites in the body, including the whole blood of healthy patients, analyzing RNA-seq data of CTSZ mRNA expression in large cohorts of subjects." (PMID 34378678, 2021). "CTSZ is overexpressed in several primary tumor types, such as PCa, colorectal, gastric, liver, melanoma, and pancreatic neuroendocrine tumors." (PMID 34378678, 2021). "CTSZ can improve adhesion and the consequent migration of T cells through the endothelia, increasing the levels of tumor-infiltrated CD8 T cells, a well-known marker of good prognosis and survival in patients with several types of cancer." (PMID 34378678, 2021). "CTSZ upregulation was also found to be significantly correlated with advanced tumor stage (P = 0.000)." (PMID 21966391, 2011). "Given the strong association of high CTSZ expression with both enhanced tumor aggressiveness and an immunosuppressive TME in PCa, CTSZ may serve not only as a prognostic biomarker but also as a therapeutic target within a theragnostic framework." (PMID 40568593, 2025). "Additionally, CTSZ promotes T cell adhesion and migration across the endothelium within the tumor microenvironment, thereby influencing CD8+ T cell infiltration—a well-recognized marker of favorable prognosis and prolonged survival across multiple cancers." (PMID 40568593, 2025). "CtsZ provided by tumor-associated macrophages is identified as a compensatory protease that can regulate the acquired tumor-promoting function of lesions lacking CtsB and CtsS." (PMID 40129966, 2025). "Our data further suggest that CTSZ may facilitate tumor progression in PCa by activating key oncogenic pathways, including STAT, VEGF, and CAM signaling." (PMID 40568593, 2025).
tumor (continued). "CTSZ, especially macrophage-specific CTSZ, correlates with the activation of epithelial-mesenchymal transition, cell cycle characteristics, and higher infiltration levels of B cells, macrophages, neutrophils, and dendritic cells in the tumor microenvironment." (PMID 38434988, 2024). "CD74‐MIF signaling plays an important role in immunosuppression, indicating that Macro_APOE/CTSZ may recruit Treg to infiltrate tumor tissue to inhibit antitumor immune responses." (PMID 36587392, 2023). "Moreover, simultaneous ablation of CTSB and CTSZ leads to synergistic anti-tumoral effects with delayed tumor onset, reduced number and size of metastases, and improved histopathological scores." (PMID 32385587, 2021). "It must be determined if the CTSZ mRNA downregulation in the blood is a feature explicitly observed for PCa patients or if it can also occur in the total blood of patients with different tumor types." (PMID 34378678, 2021). "Often, cancer cells and tumor-associated Mɸ overexpress cathepsins, such as CTSB and CTSZ." (PMID 32385587, 2021). "Cathepsin Z promotes tumor invasion by interacting with integrins and the extracellular matrix." (PMID 30245726, 2018). "CTSZ was also reported to be upregulated in gastric cancer and play a role in tumor development." (PMID 21966391, 2011). "The results indicate that Macro_APOE/CTSZ plays a substantial role in the immune dysfunction in higher‐grade tumor, and also assume a metabolic checkpoint of Macro_APOE/CTSZ, which may allow cells to return to antitumor phenotype by targeting pathway of glutamate to glutamine." (PMID 36587392, 2023). "We have also analyzed CTSZ mRNA expression in terms of different clinical parameters related to the malignancy status, and we found that the group with intermediate/high risk according to the ISUP grade group for the resected tumor presented a 71% decrease compared to the low-risk group (p=0.050)." (PMID 34378678, 2021). "Therefore, increased CREG1 levels in tumor-bearing CTSB or CTSB/CTSZ knock-out mice could mediate the reduction in tumor proliferation and invasive growth that has been consistently reported for such models." (PMID 32385587, 2021). "Indeed, analysis of cathepsin B/Z double-deficient mice in the context of the MMTV-PyMT breast cancer model revealed a strongly reduced tumor and lung metastatic burden, while a single cathepsin Z deficiency had no clear effect on the overall tumor phenotype." (PMID 22798952, 2012). "CTSZ, IFI30, CXCL8).Tumor NK cells were enriched for the d2 and d3 dog NK subclusters, classified by signaling and regulation, respectively." (PMID 41208961, 2025). "For instance, Cathepsin Z (CTSZ) and Cathepsin C (CTSC), members of the tissue proteinase family, regulate the adhesion and migration of immune cells and tumor cells." (PMID 38434988, 2024). "Upregulated cathepsin activity (CTSB, CTSD, and CTSZ) and complement pathway (C1QA, C1S) indicated pro-tumor activity by the TAMs in this region." (PMID 38217035, 2024). "Cathepsin Z (CTSZ) is a member of the cathepsin family, which has been discovered to modulate the adhesion and migratory properties of immune and tumor cells." (PMID 39169402, 2024). "The result showed that the gene expression of SLC3A1 and GLUL were highly expressed in Macro_APOE/CTSZ compared with other cell types in CRC and LC, and were upregulated in macrophage derived from tumor than normal tissues in CRC." (PMID 36587392, 2023). "Cathepsin Z (CTSZ) is a cysteine protease responsible for the adhesion and migration of both immune and tumor cells." (PMID 34378678, 2021). "Inhibition of sorcin expression can down- regulate the expression of CTSZ, MMP2, MMP9 and p-STAT3 followed by suppression of tumor growth and metastasis." (PMID 29262638, 2017). "In the context of neoplasia, there is recent in vivo evidence for a tumor-promoting role for the carboxypeptidase as well as for the RGD function of cathepsin Z." (PMID 28486971, 2017).
tumor (continued). "Real-time PCR were used to compare CTSZ expression between paired HCC tumor and non-tumor specimens." (PMID 21966391, 2011). "The peripheral levels of TRIM44, CTSZ, CD164, and TIMP1 can stimulate granulocyte production in mouse bone marrow, and high levels of TIMP1 are positively correlated with increased immune infiltration levels of tumor-infiltrating lymphocytes." (PMID 40524208, 2025). "The critical angle at which cathepsin Z could exert its influence on PTC might be its role in degrading extracellular matrix components, which might enhance tumor invasiveness." (PMID 39791166, 2025). "The tumour-promoting functions of CTSZ are not dependent on its described catalytic activity but instead are mediated by the Arg–Gly–Asp (RGD) motif in its pro-domain." (PMID 38184627, 2024). "We further found that CXCL16 was highly expressed in Macro_APOE/CTSZ and CXCR6 was expressed in Treg, which might indicate that Macro_APOE/CTSZ utilized CXCL16 signals to recruit Treg cells to the tumor site, further exacerbating the immunosuppressive TME." (PMID 36587392, 2023). "Sorcin exert its oncogenic effect by regulating key molecules such as VEGFs, MMPs, NF-κB, ERK1/ 2, CTSZ, Akt, STAT3, caspases involved in carcinogenesis and invasion of tumor cells and modulating signaling pathways including ERK, MAPK/ERK, and PI3K/Akt in various cancers." (PMID 37142981, 2023). "If CTSZ is not expressed in high levels by immune cells from the blood, they do not achieve tumor sites efficiently, and the response against cancer cells can be impaired." (PMID 34378678, 2021). "Furthermore, cathepsin Z is essential for the activation of focal adhesion kinase (FAK) and SRC and, furthermore, cathepsins regulate tumor angiogenesis." (PMID 30669448, 2019). "Many studies have shown that CTSZ is related with the EMT, which could promote invasion and migration in tumor." (PMID 29262638, 2017). "CTSZ gene was stably transfected into HCC line QGY-7703 cells and its role in tumorigenicity and cell motility was characterized by soft agar, wound-healing, transwell invasion and cell adhesion assay, and tumor xenograft mouse model." (PMID 21966391, 2011). "Interestingly, several of the tumor-promoting functions of CTSZ were not dependent on its described catalytic activity." (PMID 29262638, 2017). "The RQ of CTSZ in tumor and nontumor were then subjected to the following statistical analysis, and the result confirmed that the expression level of CTSZ was significantly higher in tumor tissues than that in their paired nontumorous liver tissues (P = 0.000, n = 137)." (PMID 21966391, 2011). "Although we failed to found significant correlation between CTSZ upregulation and metastasis related features, we did found that higher percentage (51%) of patients without tumor encapsulation has got CTSZ upregulation than that (34.8%) of patients with encapsulation." (PMID 21966391, 2011). "We therefore hypothesize that CTSZ may contribute to the formation of an immunosuppressive TME by enhancing the recruitment and activation of these immune-inhibitory cell types, potentially through modulation of tumor-derived chemokines or downstream signaling pathways." (PMID 40568593, 2025).